S100A6 (S100 calcium binding protein A6)
Diseases named in the same sentence as S100A6 in open-access papers (continued):
Sharing a sentence is not in itself a finding about the gene and the disease.
Alzheimer disease (11 papers, 2010 to 2024). A progressive, neurodegenerative disease characterized by loss of function and death of nerve cells in several areas of the brain leading to loss of cognitive function such as memory and language. "S100A6 is linked to a variety of neurodegenerative diseases such as Alzheimer’s disease, amyotrophic lateral sclerosis, also called motoneuron disease, and disorders associated with aging." (PMID 28068373, 2017). "Prenatal stress also down-regulated S100a6 encoding a calcium-binding protein related to cell signaling and ion transport in astrocytes and involved in Alzheimer's disease, Down syndrome and amyotrophic lateral sclerosis." (PMID 24651125, 2014). "Of note, increased expression of S100B, S100A4, S100A6, S100A8, and S100A9 has also been linked with Alzheimer's disease." (PMID 38737767, 2024). "Intriguingly, S100A6 overexpression in astrocytes has been observed near amyloid plaque deposits in Alzheimer's disease patients and Alzheimer's disease transgenic mouse models." (PMID 34658843, 2021). "It has also been reported that an increase of S100a6 is normally present in some neurodegenerative diseases (e.g., Alzheimer’s disease) depending on the regulation of the HPA-axis." (PMID 32183190, 2020). "In contrast, in the brain of APP23 mice, a mouse model for Alzheimer’s disease, S100B, S100A6, and S100A8 show co-localization with Aβ plaques, compatible with astrocyte activation, and the expression level of S100A8 is increased in neural cells." (PMID 31281238, 2019). "Some S100 proteins, such as S100A6 and S100B, play a prominent role in neurodegenerative disorders, including Alzheimer's disease (AD)." (PMID 24586443, 2014). "In dementia common in the elderly population, such as Alzheimer’s disease, astrocytic S100A6 is homogeneously up-regulated within the white matter and in the neocortex, almost all S100A6 immunoreactivity is concentrated in astrocytes surrounding the amyloid beta deposits of senile plaques." (PMID 28068373, 2017). "Among them S100B, S100A6, S100A9 and S100A12 have been linked to Alzheimer's Disease." (PMID 20672051, 2010). "S100a6 is overexpressed in mouse models of amyotrophic lateral sclerosis (ALS) and Alzheimer’s disease and is speculated to contribute to disease progression via its high affinity for zinc." (PMID 28587098, 2017). "Interestingly, it was found that S100A6 might influence the phosphatase activity of CacyBP/SIP towards tau, a protein involved in Alzheimer’s disease pathology." (PMID 28068373, 2017).
endometrial cancer (11 papers, 2001 to 2025). Primary or metastatic malignant neoplasm involving the endometrium (mucous membrane that lines the endometrial cavity). "Overexpression of CTSB, CALU, S100A6, LDHA, and HNRNPA1 in endometrial cancer tissues was validated by WB, and IHC showed an intense cytoplasmic and nuclear staining of S100A6 in tumor samples." (PMID 39194522, 2024).
osteosarcoma (10 papers, 2009 to 2023). A usually aggressive malignant bone-forming mesenchymal neoplasm, predominantly affecting adolescents and young adults. "By contrast, elevated levels of S100A6 decreased the mobility of osteosarcoma cells and were associated with decreased clinically evident metastases." (PMID 19888321, 2009). "Regarding osteosarcoma, the latest study has shown that S100A6 overexpression increased the proliferation and reduced the osteogenic differentiation of osteosarcoma cells." (PMID 36674873, 2023). "Previous research has demonstrated that when S100A6 binds to RAGE, it causes apoptosis in epithelial cells by activating Jun N-terminal kinase and plays a crucial role in osteosarcoma metastasis." (PMID 36232318, 2022). "The expression and prognostic role of S100A6 have been identified in thyroid, colorectal, and osteosarcoma cancers." (PMID 29607329, 2018). "The only other published study, which to our knowledge examined the effect of S100A6 on motility, showed a decrease in the motility of one of three osteosarcoma cell lines after adenoviral-mediated overexpression of S100A6." (PMID 19724273, 2009). "Some studies have shown that S100A6 is overexpressed in human osteosarcoma." (PMID 37670392, 2023). "The influence of S100A6 on the phenotypes of osteosarcoma cells, such as adhesion, migration, and invasion, may be inextricably related to its cytoskeletal regulation." (PMID 37670392, 2023). "This suggests that S100A6 inhibits the osteogenic differentiation of osteosarcoma." (PMID 37670392, 2023). "In addition, the level of S100A6 correlated with tumor metastasis in osteosarcoma and prostate cancer." (PMID 36674873, 2023). "lncRNA DARS-AS1 promotes the progression of osteosarcoma by regulating miR-532-3p/CCR7; lncRNA BACE1-AS regulates the proliferation, migration, and invasion of osteosarcoma cells through the miR-762/SOX7 axis; lncRNA SNHG1 promotes osteosarcoma progression by upregulating S100A6 through miR-493-5p." (PMID 36388161, 2022). "The identified immune-related predictive signature, including CD70, TNFRSF9, EGFR, PDGFD and S100A6, will facilitate the development of personalized therapy for osteosarcoma and provide new insights into the role of the tumor immune microenvironment in regulating patients’ responses to chemotherapy." (PMID 34016089, 2021). "An earlier study using MVs from human osteosarcoma Saos-2 cells showed the presence of S100A4 and S100A6 but not S100A11." (PMID 36979349, 2023).
prostate carcinoma (10 papers, 2004 to 2023). A carcinoma that arises from epithelial cells of the prostate gland. "S100A6 and S100A2 are the two calcium-binding proteins that are mostly down-regulated in prostate cancer, and the underlying mechanism responsible for it appears to involve hypermethylation of S100A6 and S100A2." (PMID 36765652, 2023). "In contrast to the increased expression in other tumors, loss of S100A6 protein expression is very common in the development of prostate cancer, which may occur at an early stage." (PMID 37670392, 2023). "The finding of intense S100A6 expression in the basal cells of benign glands but loss of expression in cancer could be useful as a novel diagnostic marker for prostate cancer." (PMID 15280928, 2004). "Our data suggest that loss of S100A6 protein expression is common in prostate cancer development and may occur at an early stage." (PMID 15280928, 2004). "S100A6 expression loss may be a useful diagnostic method for prostate cancer." (PMID 37670392, 2023). "Other S100 proteins are downregulated in tumours and have putative tumour suppressor roles, including S100A2 and S100A6 in prostate cancer." (PMID 17579622, 2007). "We therefore examined the tissue expression of S100A6 in benign, malignant and metastatic prostate tissues and in prostate cancer cell lines." (PMID 15280928, 2004). "Other than one recent report showing S100A6 expression in ∼20% of prostatic cancers arranged on a tissue-microarray, there are no reports investigating S100A6 expression in benign and malignant prostate tissues or cell lines." (PMID 15280928, 2004). "Further studies regarding the expression of S100A6 in prostate cancer and other tumours are clearly warranted." (PMID 15280928, 2004). "The aim of our study was to investigate the involvement of S100A6 during prostate cancer development and progression." (PMID 15280928, 2004). "For example, S100A6 was lowly expressed in prostate cancers, which might be related to promoter hypermethylation of S100A6." (PMID 18793447, 2008). "In other tumour types, S100A6 has also been reported to be hypermethylated in prostate cancer." (PMID 17579622, 2007). "The pattern of S100A6 expression in benign epithelium and adenocarcinomas is similar to that of cytokeratin 5 and that reported for p63 and 34βE12, and therefore has the potential to be used as an adjuvant to these markers in the diagnosis of prostate cancer." (PMID 15280928, 2004). "Using immunohistochemistry, the expression of S100A6 was examined in benign (n=66), premalignant (n=10), malignant (n=66) and metastatic prostate (n=5) tissues arranged in a tissue-microarray or whole sections as well as in prostate cancer cell lines." (PMID 15280928, 2004). "However, in contrast, S100A6 expression in prostate cancer has been reported to be decreased." (PMID 28423550, 2017). "Nevertheless, the finding of S100A6 expression in some prostate cancer cell lines but not others provides a useful tool to further understand the mechanism(s) involved in regulating S100A6 expression." (PMID 15280928, 2004). "Therefore, S100A6 immunohistochemistry could represent a novel marker for basal cells in the benign prostate and its absence in malignant cells may be useful as an adjuvant method to p63 and 34βE12 immunostaining to facilitate the pathological diagnosis of prostate cancer." (PMID 15280928, 2004).
amyotrophic lateral sclerosis (9 papers, 2013 to 2023). Amyotrophic lateral sclerosis (ALS) is a neurodegenerative disease characterized by progressive muscular paralysis reflecting degeneration of motor neurons in the primary motor cortex, corticospinal tracts, brainstem and spinal cord. "In the case of amyotrophic lateral sclerosis, which is characterized by the degeneration of motoneurons that control muscle movement, S100A6 is selectively up-regulated within astrocytes surrounding the neurodegenerative lesions." (PMID 28068373, 2017). "Interestingly, S100A6 upregulation in astrocytes has been observed in patients suffering from amyotrophic lateral sclerosis (ALS), and around amyloid plaque deposits in AD patients and transgenic AD model animals." (PMID 31440382, 2019). "High/increased S100A6 level may also be an indication of astrogliosis, a pathological change observed in neurodegenerative diseases such as Alzheimer disease or amyotrophic lateral sclerosis (ALS)." (PMID 36674873, 2023). "For instance, in amyotrophic lateral sclerosis (ALS), S100A6 was found to be overexpressed within astrocytes surrounding the neurodegenerative lesions." (PMID 32492924, 2020). "In addition, in a transgenic mouse model of amyotrophic lateral sclerosis (ALS), it was found that reactive astrocytes (not motor neurons) highly expressed S100A6 in several regions (including 12 pairs of nerve roots) in the brain stem, while S100A6 was negative in the sublingual nucleus." (PMID 37670392, 2023).
ovarian carcinoma (9 papers, 2008 to 2026). A malignant neoplasm originating from the surface ovarian epithelium. "Serum S100A6 concentration has been found that it predicts peritoneal tumor burden and is associated with advanced stage in ovarian cancer." (PMID 30558666, 2018). "CONCLUSIONS: Our data provides novel insights regarding the clinical implications of S100A6 expression in ovarian cancer, providing strong rationale for functional investigations of S100A6 in ovarian cancer." (PMID 41673585, 2026). "IHC, in vivo bioluminescent imaging, and a modified ELISA assay (ECLISA) were used to show the potential of protein S100A6 as a clinically relevant ovarian cancer biomarker." (PMID 37301378, 2023). "Nevertheless, in our study, high expression of S100A6 predicted favorable OS in ovarian cancer patients, especially in serous type ovarian cancer." (PMID 30558666, 2018). "Using a method for low molecular weight protein enrichment, followed by liquid chromatography and mass spectrometry analysis, a human-specific peptide sequence of S100A6 was identified in sera from mice with advanced-stage experimental ovarian carcinoma." (PMID 19888321, 2009). "The result from the animal model was confirmed in human clinical material as S100A6 was found to be significantly elevated in the sera from women with advanced stage ovarian cancer compared to those with early stage disease." (PMID 19888321, 2009). "S100A6 expression was documented in cancer xenografts as well as from ovarian cancer patient tissues." (PMID 19888321, 2009). "Lastly, we sought to validate the expression profile of S100A6 in human sera using a well-controlled clinical study set of women with early and advanced stage ovarian cancers." (PMID 19888321, 2009). "Additionally, S100A6 expression in an ovarian cancer cohort from The Cancer Genome Atlas (TCGA) PanCancer dataset (n = 299) was evaluated and associations with overall survival and progression-free survival were identified." (PMID 41673585, 2026). "The data signify that S100A6 may prove useful in detecting and/or monitoring ovarian cancer, when used in concert with other biomarkers." (PMID 19888321, 2009). "Thus, we suggest that S100A6 may play different roles in early and late stage ovarian cancer patients." (PMID 30558666, 2018). "In ovarian cancer, many S100 family members have been reported, such as S100A1, S100A4, S100A6, S100B and S100P." (PMID 30558666, 2018). "A comparison of endothelial cells between healthy ovarian and ovarian cancer tissues revealed that genes such as RACK1, S100A6, and C1orf186 were significantly upregulated, while GMB2L1, TM4SF1, and EIF1 were significantly downregulated in the ovarian cancer samples." (PMID 37124501, 2023). "However, the role of S100A6 in ovarian cancer is not well established." (PMID 41673585, 2026).
hepatocellular carcinoma (8 papers, 2008 to 2025). A malignant tumor that arises from hepatocytes. "In several human carcinomas, the expression of S100A6 appears to be associated with aggressive disease and high levels of S100A6 was an independent marker for poor prognostic, such as colorectal, gastric, thyroid, hepatocellular carcinoma, and so on." (PMID 30558666, 2018). "S100A6 expression was also helpful in discriminating between various cancer types, as in the case of cholangiocarcinoma and hepatocellular carcinoma." (PMID 36674873, 2023). "Differences in S100A6 level proved to also be useful for the discrimination between primary liver tumors such as hepatocellular carcinoma and metastases derived from colorectal carcinoma." (PMID 36674873, 2023). "It is reported that increased expression of S100A6 can promote cell proliferation and migration in human hepatocellular carcinoma." (PMID 25799022, 2015). "The upregulation of PLAUR, S100A4, S100A6, and FGFR1 in mature B cells was involved in disease‐associated cellular migration and tissue invasion, which may influence hepatocellular carcinoma with persistent liver injury." (PMID 41190282, 2025). "In this context, it was recently suggested that differences in S100A6 expression might help to distinguish between cholangiocarcinoma and hepatocellular cancer as S100A6 expression levels were described to be up-regulated in CCA tumor tissue but normal in HCC tissue samples." (PMID 27709523, 2016). "Finally, serum concentration levels of S100A6 were also not significantly altered in patients with hepatocellular carcinoma." (PMID 27709523, 2016). "In cholangiocarcinoma, increased expression levels of S100A6 mRNA and protein were found in a small cohort of tissue specimens of intrahepatic CCA and it was suggested that S100A6 may help to differentiate between intrahepatic CCA and hepatocellular carcinoma (HCC)." (PMID 27709523, 2016). "Moreover, S100A6 mRNA was significantly elevated in cholangiocarcinoma (CCA), while no significant increase was observed in hepatocellular carcinoma (HCC)." (PMID 37670392, 2023).
liver fibrosis (8 papers, 2019 to 2025). "Key molecules associated with liver fibrosis and inflammation (Cd34, Epcam, S100a6, Fhl2, Itgax, and Retnlg) were up-regulated at both the gene and protein levels." (PMID 38076459, 2023). "Recently, S100A6 expression has been shown to be highly correlated with CCl4-induced liver fibrosis in mice." (PMID 36674873, 2023). "S100A4 is a driver of the fibrotic response in tendon, and S100A6 has a similar role in liver fibrosis, although the role of S100A6 in tendon, if any, is unknown." (PMID 40224957, 2025). "By stimulating proinflammatory cascades by inflammatory gene expressing and profibrogenic cytokine releasing including Il1b, Tnf, Lgals3, S100a6, S100a4, S100a11, and S100a10, Mac1 was characterized as one of the profibrotic contributors during the liver fibrosis progression." (PMID 37724132, 2023). "In contrast to S100A6, the soluble receptor for advanced glycation end products (sRAGE), a natural antagonist of the S100A6/RAGE pathway, had a preventative effect on liver fibrosis in the same mouse model." (PMID 36674873, 2023). "For instance, we identified S100A6 as a novel marker of activated MFB, following liver fibrosis, which could be confirmed in vitro." (PMID 31137713, 2019). "The APASHA model—consisting of APOF, PCSK9, AFM, S100A6, HbA1c %, and AZGP1—showed an excellent discriminatory capacity with an AUROC of 0.8875 (CI 0.82–0.96) to discriminate MASH, but not liver fibrosis." (PMID 40250425, 2025).
neuroblastoma (8 papers, 2011 to 2025). Neuroblastoma (NB) is the most common solid, extracranial childhood tumor. "To confirm their transcriptional activity, we used a Neuro 2A, a mouse neuroblastoma cell line, to perform luciferase assay using the promoters of S100A6 and S100A11." (PMID 40882002, 2025). "The authors performed immunohistochemical staining of cryosections from neuroblastoma tissues using antibodies specific for markers of S- and N-type cells, S100A6 (calcyclin) and neurofilaments, respectively." (PMID 30116755, 2018). "RAGE engagement by S100A6 in neuroblastoma cells also induced cell death via JNK phosphorylation with ROS generation." (PMID 29880821, 2018). "In all neuroblastoma cell lines tested, expression of S100A6 was significantly up-regulated following exposure to either drug." (PMID 28206967, 2017). "In human SH-SY5Y neuroblastoma cells, S100A6 bound to RAGE triggers the JNK and caspase pathways, resulting in apoptosis." (PMID 21559403, 2011). "S100A6 has also become a marker for glial precursor cells in neuroblastoma." (PMID 39796257, 2025). "Moreover, it has been indicated that S100-A6 can trigger neuronal apoptosis by causing ROS-dependent activation of JNK and of caspases −3 and −7 in SH-SY5Y neuroblastoma cells." (PMID 33800305, 2021). "We speculate that the increased expression of S100A6 following exposure to anticancer drugs demonstrated in our study may indicate a protective role for this protein in neuroblastoma cells and thus suggest this protein as a potential therapeutic target for combined chemotherapy strategies." (PMID 28206967, 2017). "S100A6 activates c-Jun NH2-terminal kinase, triggering apoptosis and ROS production, thus regulating RAGE-dependent survival in neuroblastoma cells." (PMID 39796257, 2025). "Moreover, expression of crucial regulators of calcium signaling, such as IP3R3, RYR3 and S100A6, are deregulated upon CDDP or TOPO treatment of neuroblastoma cells." (PMID 28206967, 2017). "This was also investigated in IMR-32 cells that confirmed the up-regulation of S100A6; IP3R3 and RYR3 but showed no down-regulation of RYR1 in CDDP treated neuroblastoma cells." (PMID 28206967, 2017).